PLCD1 (phospholipase C delta 1)
Diseases named in the same sentence as PLCD1 in open-access papers (continued):
Sharing a sentence is not in itself a finding about the gene and the disease.
chondrosarcoma (1 paper, 2022). A malignant cartilaginous matrix-producing mesenchymal neoplasm arising from the bone and soft tissue. "PLCD1 overexpression in high-grade chondrosarcoma suppressed CDKs/cyclins and induced DNA damage causing cell cycle blocking and apoptosis." (PMID 35836489, 2022). "Our results demonstrated that overexpressed PLCD1 downregulated CDKs and interacted cyclins to prove a prolonged cell cycle in chondrosarcoma cells." (PMID 35836489, 2022). "A lower PLCD1 expression was mainly found in high-grade chondrosarcoma and was verified by western blotting." (PMID 35836489, 2022). "PLCD1 overexpression blocks the cell cycle at the G1/S phase, and PLCD1 knockdown has an opposite effect on the cell cycle of chondrosarcoma." (PMID 35836489, 2022). "Compared with the TCGA database, our immunohistochemical results of chondrosarcoma tissue microarray (49 samples) revealed the relation between PLCD1 expression and malignance of chondrosarcoma, compared with H&E." (PMID 35836489, 2022). "In conclusion, our study finds out that PLCD1 protein shows antitumor effect on chondrosarcoma via inhibiting cell proliferation." (PMID 35836489, 2022). "Our results demonstrated that PLCD1 knockdown in chondrosarcoma cells in vitro promoted cell proliferation by enhancing the cell cycle." (PMID 35836489, 2022). "Our results demonstrated that PLCD1 overexpression in chondrosarcoma cells in vitro inhibits cell proliferation by arresting the cell cycle at the G1/S phase." (PMID 35836489, 2022). "Compared with the TCGA database, the relation between PLCD1 expression and the malignancy of chondrosarcoma was demonstrated." (PMID 35836489, 2022). "Our results demonstrate that the upregulation of DNA damage response proteins suggests enhanced DNA repair occurring in PLCD1 overexpressed chondrosarcoma cells." (PMID 35836489, 2022). "Animal xenografts were established to verify the effect of PLCD1 in high-grade chondrosarcoma." (PMID 35836489, 2022). "PLCD1 may be a novel marker for the diagnosis of chondrosarcoma and classification of its malignancy." (PMID 35836489, 2022). "Our study aimed to explore the PLCD1 function in chondrosarcoma for further treatment." (PMID 35836489, 2022). "A lower PLCD1 expression was detected mainly in high-grade chondrosarcoma." (PMID 35836489, 2022). "Antiproliferation of PLCD1 reminds us that it may be a novel target for the treatment of high-grade chondrosarcoma, and our study aims to explore the function of PLCD1 protein in high-grade chondrosarcoma." (PMID 35836489, 2022). "Our results demonstrate that PLCD1 overexpression can inhibit cell proliferation of chondrosarcoma." (PMID 35836489, 2022). "In addition, cell apoptosis detected by flow cytometry analysis suggests the PLCD1 overexpressed chondrosarcoma cells failed to repair DNA damage and caused the programmed cell death." (PMID 35836489, 2022). "And PLCD1-induced DNA damage might enhance the chemotherapy sensitivity of chondrosarcoma." (PMID 35836489, 2022). "PLCD1 could be a novel target in high-grade chondrosarcoma for further drug development." (PMID 35836489, 2022). "Drugs such as PLCD1 agonists might be useful for chondrosarcoma treatment." (PMID 35836489, 2022). "We hypothesized PLCD1 overexpression induced DNA damage in chondrosarcoma cells." (PMID 35836489, 2022). "We further detected the PLCD1 expression in the CCLE database and chondrosarcoma cell lines (HCS-2/8 and SW1353)." (PMID 35836489, 2022).
colorectal tumor (1 paper, 2023). "Studies have confirmed that overexpression of PLCD1 can promote the apoptosis of colorectal tumor cells, arrest the cell cycle at G1 / S phase, and inhibit proliferation, invasion and migration of colorectal tumor cells." (PMID 37460940, 2023).
endometriosis (1 paper, 2021). The growth of functional endometrial tissue in anatomic sites outside the uterine body. "Whereas, in the differentially expressed gene analysis, the tumor related genes TEX41, POLQ, and FLT1 were highly expressed in the ectopic endometrial cell group of endometriosis, and the expression of tumor suppressor gene PLCD1 was down-regulated when compared with the control group." (PMID 33868805, 2021).
lung adenocarcinoma (1 paper, 2021). A carcinoma that arises from the lung and is characterized by the presence of malignant glandular epithelial cells. "We therefore analyzed the CPTAC protein dataset for DLC1, Caveolin-1 and PLCD1 expression in lung adenocarcinoma and lung squamous cell carcinoma compared to adjacent normal lung." (PMID 34727930, 2021).
lung carcinoma (1 paper, 2021). "As reported for the rat DLC1 homolog, immunoprecipitation studies confirmed complex formation between PLCD1 and DLC1 in H1703 cells, a human lung cancer cell line that expresses readily detectable levels of both proteins, as well as between PLCD1 and Caveolin-1." (PMID 34727930, 2021).
Meckel syndrome (1 paper, 2025). "We co-expressed this integrated, multicopy mNG::PLCδ1-PH transgene with mScarlet-tagged MKS-2 (MKS-2::mSc), a protein in the Meckel syndrome (MKS) complex that localizes to the TZ." (PMID 41064964, 2025).
Obesity (1 paper, 2016). Accumulation of substantial excess body fat. "This pathway included genes upregulated in IB piglets, which were involved in adipogenesis and in the development of obesity, as NFATC1 and PLCD1." (PMID 27936208, 2016).
oral squamous cell carcinoma (1 paper, 2023). "MicroRNA-191 regulates oral squamous cell carcinoma cells growth by targeting PLCD1 via the Wnt/β-catenin signaling pathway." (PMID 37460940, 2023).
renal carcinoma (1 paper, 2023). A carcinoma arising from the epithelium of the renal parenchyma or the renal pelvis. "Similar low mutation rates of PLCD1 was found, with 0.4% (1/249) in KIRC and 0.5% (1/207) in non-KIRC renal carcinoma." (PMID 36849889, 2023).
renal cell carcinoma (1 paper, 2023). "PLCD1 plays a pivotal role in tumor suppression of several types of cancers; however, its expression and underlying molecular mechanisms in renal cell carcinoma (RCC) pathogenesis remain elusive." (PMID 36849889, 2023).
squamous cell carcinoma (1 paper, 2016). A carcinoma arising from squamous epithelial cells. "Potential tumor suppressor genes, also found in other squamous cell carcinomas, have been discovered in the lost regions 2q33-q37.3 (PLCD4), 3p26.3-q11.1 (RBMS3, PLCD1, and CACNA2D3) and 11q12.2-q25 (CPT1A, CCND1, FGF4/FGF3, and PPP2R1B)." (PMID 26901676, 2016).
tumor syndromes (1 paper, 2020). "Our findings, along with those of Horer, show that the germline variant and the somatic mutation were on the same allele of PLCD1 was surprising as it is inconsistent with the currently accepted model for tumor syndromes caused by tumor suppressor genes (Knudson’s two hit hypothesis)." (PMID 32265483, 2020).
tumor (21 papers, 2011 to 2025). "On the other hand, only rare mutations of PLCD1 were observed in RCC tumor tissues, indicating that PLCD1 silencing is the predominant type of PLCD1 inactivation in RCC." (PMID 36849889, 2023). "Our results indicate that familial trichilemmal cysts is an autosomal dominant tumor syndrome resulting from two hits to the same allele of PLCD1 tumor suppressor gene." (PMID 32265483, 2020). "Moreover, PLCD1 downregulation is of clinical significance, substantially associated with tumor stage and distant metastasis of KIRC and KIRP patients in TCGA database." (PMID 36849889, 2023). "Similarly, PLCD1, which encodes a member of the phospholipase C family, has higher expression in the stage 1 tumors consistent with reports in several tumor types that it is a tumor suppressor gene." (PMID 26893359, 2016). "The ectopic expression of PLCD1 decreases tumor cell motility by modulating cytoskeletal recombinant proteins, including RhoA and phospho-cofilin." (PMID 37685980, 2023). "We also validated the tumor suppressive roles of PLCD1 with multiple biological assays, which is achieved by suppressing Wnt/β-catenin and EGFR-FAK-ERK signaling in RCC cells." (PMID 36849889, 2023). "By analyzing theTIMER2.0 database, we found differential expression of PLCD1 between tumor and adjacent tissues across TCGA tumors." (PMID 36849889, 2023). "Our results demonstrate that PLCD1 functions as a tumor suppressor in RCC cells, consistent with previous reports in other types of carcinomas." (PMID 36849889, 2023). "PLCD1 is also identified as a new tumor suppressor gene, which is suppressed by promoter methylation in various cancer types." (PMID 37033945, 2023). "In vivo animal tests further proved these conclusions that overexpressed miR-191 promoted tumor growth and invasion in nude mice by inhibiting PLCD1, and decreasing miR-191 expression promoted PLCD1 and reduced tumor growth and infiltration in nude mice." (PMID 37460940, 2023). "The results confirmed DLC1, Caveolin-1 and PLCD1 protein levels were lower in tumor tissue compared to normal adjacent lung." (PMID 34727930, 2021). "The tumor suppressor roles played PLCδ1 in ESCC does not only end in inhibiting cell growth but also their ability to inhibit cell migration." (PMID 32276377, 2020). "Remarkably, 21 of 21 trichilemmal cysts from 16 subjects all harbored a somatic p.S745L (c.2234 G > A) mutation in phospholipase C delta 1 (PLCD1), a proposed tumor suppressor gene." (PMID 32265483, 2020). "The anti-tumor roles played by PLCδ1 in ESCC included the induction of a cell cycle arrest at the G1/S phase via the upregulation of p21 and the downregulation of Akt phosphorylation." (PMID 32276377, 2020). "Significantly, in comparison with the control groups, the administration of Myr-PLCδ1 peptide appeared to reduce tumor weight at the end of treatment." (PMID 28576130, 2017). "Our data showed that administration of Myr-PLCδ1 compared to that of the control peptide robustly inhibited distant lung metastasis accompanied with a reduced tumor growth of MDA-MB-231 cells at the primary site in tumor-bearing mice 3 weeks post-treatment." (PMID 28576130, 2017). "Promoter methylation analyses of PLCD1 and PLCE1 performed in cell lines and tumor biopsies revealed that methylation of PLCD1 can contribute to reduced expression in 40% of the microsatellite instable carcinomas." (PMID 21909432, 2011). "In contrast, tumor‐suppressive circRNAs, specifically circ‐0004018, circ‐0072309, circ‐0000520, and circ‐PLCD1, can diminish PI3K/AKT by upregulating PTEN or downregulating IGF1R, resulting in decreased proliferation, invasion, and increased responsiveness to treatments such as herceptin." (PMID 40740483, 2025). "In addition, PS binding contributes to the interaction of DLC1-START with Caveolin-1 and PLCD1, and to the tumor suppressor functions of DLC1 that are RhoGAP-independent." (PMID 34727930, 2021).
tumor (continued). "Anti-tumour effects have been reported for PLCD1 in multiple cancers." (PMID 28423710, 2017). "Mounting evidence therefore suggests that PLCD1 functions as a tumour suppressor." (PMID 28423710, 2017). "In this study, PLCD1 negatively regulated pGSK-3β, active-β-catenin and MMP7, suggesting for the first time that the β-catenin signalling pathway may be involved in the anti-tumour activity of PLCD1." (PMID 28423710, 2017). "Several groups have suggested a role for PLCD1 in regulating the cell cycle G1/S-checkpoint, however, there are contradicting results to whether it has an oncogenic or tumor suppressive function." (PMID 21909432, 2011). "Our results demonstrate that PLCD1 is a potent tumor suppressor frequently inactivated by promoter methylation in RCC and exerts its tumor suppressive functions via suppressing WNT/β‐catenin and EGFR‐FAK-ERK signaling." (PMID 36849889, 2023). "In this study, we identified PLCD1 as a functional TSG downregulated by promoter CpG methylation in RCC, and it exerts tumor suppressor effects by blocking WNT/β-catenin and EGFR-FAK-ERK signaling." (PMID 36849889, 2023). "We also constructed a prognostic risk model using the four LMRGs signatures, including ENPP2, MGLL, PLCD1, and SLC44A3, and we found that most of them were correlated with tumor progression." (PMID 37033945, 2023). "We further revealed the antitumor effect of PLCD1 overexpression in HCS-2/8 in vivo, and Western blotting of the tumor tissue verified the downregulation of CDKs and interacted cyclins." (PMID 35836489, 2022). "Overall, the interaction between DLC1-START, Caveolin-1, PLCD1, and phosphatidyserine (PS) contributes to DLC1 tumor suppressor function(s) in a RhoGAP-independent manner." (PMID 34727930, 2021). "In our investigation, PLCD1 and PLCD3 were found to be high expressed in PAAD tumor tissue compared with normal tissue." (PMID 31808619, 2020). "In our investigation, PLCD1 and PLCD3 were found to be highly expressed in PAAD tumor tissue, compared with normal tissue." (PMID 31808619, 2020). "In the present study, PLCD1, pERK1/2, active-β-catenin and MMP7 protein levels were measured by immunohistochemistry (IHC) in these tumours." (PMID 28423710, 2017). "The present data support a tumor suppressive role of PLCD1 and PLCE1 in CRC, which for PLCD1 possibly can be explained by an epigenetic mechanism in microsatellite unstable carcinomas." (PMID 21909432, 2011). "Inhibition of miR-191 increase PLCD1, and then decrease β-catenin, MMP-9, C-myc, N-cadherin, CDK4 and PCNA, ultimately leading to the decrease of proliferation, migration and invasion of OSCC cells, thus exerting anti-tumor effects." (PMID 37460940, 2023). "The expression levels of PLCD1 and PLCE1 were correlated, and as expected, reduced expression of both genes was associated to more advanced tumor stages (data not shown)." (PMID 21909432, 2011). "However, work is still moving forward for the reason that there still is no PLCD1 agonist now and PLCD1 deletion usually happens in tumor cells." (PMID 35836489, 2022).
cancer (17 papers, 2011 to 2025). A tumor composed of atypical neoplastic, often pleomorphic cells that invade other tissues. "Data from TIMER2.0 database showed that PLCD1 manifested rare mutations across a spectrum of TCGA cancers, with only 0.54% (2/370) in KIRC patients." (PMID 36849889, 2023). "Rho-GTP, cell proliferation, cell migration, and/or anchorage-independent growth assays were used to investigate the contribution of PS and PLCD1, or the implications of TCGA cancer-associated DLC1-START mutants, to DLC1 functions." (PMID 34727930, 2021). "Relative to adjacent normal tissues, PLCD1 exhibited significant lower expression in many types of cancers, including RCC." (PMID 36849889, 2023). "We and others previously discovered that several 3p22-21.3 genes including RASSF1A, BLU, DLEC1, ZMYND10 and PLCD1 were frequently methylated in various cancers." (PMID 36849889, 2023). "The antioxidant gene CAT was upregulated, along with PLCD1, which is involved in immune signal transduction and plays a role in cancer suppression." (PMID 31569385, 2019). "PLCD1, which is involved in immune signal transduction and plays a role in cancer suppression, was also upregulated." (PMID 31569385, 2019). "Several studies have shown that PLCD1 has anti-cancer effects." (PMID 37460940, 2023). "However, despite evidence of the oncosuppressor function of PLCδ1, there is still little knowledge about the activity of PLCδ3, whose activation in cancer cells is still poorly defined and controversial." (PMID 35159043, 2022). "Therefore, the PPI of the Gαh/PLCδ1 complex is not only critical for relaying TNBC metastasis but also serves as a useful target for developing anti-cancer agents against metastatic TNBCs." (PMID 28576130, 2017). "Therefore, methylation appears to be the main driver of PLCD1 disruption in cancer patients." (PMID 36849889, 2023).
infection (3 papers, 2014 to 2023). The state of being infected such as from the introduction of a foreign agent such as serum, vaccine, antigenic substance or organism. "Similarly, a number of genes placed in “Axonal guidance”, including several modulated by infection (SLIT2, PLCD1, SLIT-ROBO Rho GTPase-activating protein 2 (SRGAP2) and TUBA4A), showed elevated expression." (PMID 37276213, 2023). "Of these, CD44, KDM1B, FKBP4, TEF, SYT4, SATB1 and PLCD1 are reported to be involved in the inflammatory reaction; for the remaining ten genes, there have been no reports concerning inflammation or infection." (PMID 34046191, 2021). "The radial profile of PLCδ1 movement showed that the movement is highest near the cell membrane irrespective of infection status of the cell." (PMID 25474261, 2014).
PLCD1 also shares sentences with these, for which no sentence is quoted: bladder cancer (2 papers); trichilemmal cysts (2); Anonychia (1); atrioventricular block (1); cardiac ischemia (1); fibrosis (1); focal cortical dysplasia type II (1); Infertility (1); invasive ductal carcinoma (1); lung and (1); lung squamous cell carcinoma (1); lymph node metastasis (1); male fertility (1); male infertility (1); metastatic disease (1); neurodegenerative disease (1); non-small cell lung carcinoma (1); onychodystrophy (1); prostate carcinoma (1); skin tumors (1); tuberous sclerosis complexes (1).